G6PD (glucose-6-phosphate dehydrogenase)
Diseases named in the same sentence as G6PD in open-access papers (continued):
Sharing a sentence is not in itself a finding about the gene and the disease.
PK deficiencies (2 papers, 2023 to 2024). "In the literature search, no article was found in which new-generation inflammatory markers, such as systemic immune inflammation index (SII), NLR, and platelet-to-lymphocyte ratio (PLR) were studied in G6PD and PK deficiency in neonatal prolonged jaundice." (PMID 39336532, 2024). "The aim of this study was to evaluate the clinical findings of G6PD and PK deficiency in prolonged jaundice." (PMID 39336532, 2024). "Among the enzymopathies, G6PD and PK deficiencies are the most common defects in diverse ethnic groups." (PMID 39336532, 2024). "We also aimed to evaluate the relationship between G6PD and PK deficiency and new-generation inflammatory markers (SII, NLR, PLR) in neonatal prolonged jaundice." (PMID 39336532, 2024). "Usually, RBC enzymopathy cannot be diagnosed by PB smear testing alone, because RBC morphology is not specific in individuals with G6PD or PK deficiencies." (PMID 36832257, 2023).
polycythemia (2 papers, 2018 to 2024). Abnormally high mass or concentration of red blood cells in the blood, either due to an increase in erythropoiesis or a decrease in plasma volume. "Blood investigations showed secondary polycythemia, Glucose-6-Phosphate Dehydrogenase (G6PD) within normal levels, and methemoglobin at around 3.9–7.1%." (PMID 39224766, 2024). "The causes of jaundice were physiological jaundice in 62 (41%) newborns, ABO incompatibility in 45 (30%), Rh incompatibility in 10 (6.6%), G6PD in 14 (9.3%), polycythemia in 13 (8.6%), and cephalohematoma in 7 (4.6%)." (PMID 29755532, 2018).
renal carcinoma (2 papers, 2019 to 2024). A carcinoma arising from the epithelium of the renal parenchyma or the renal pelvis. "We verified the expression of G6PD and GAPDH in distinct renal cancer cell lines." (PMID 39034372, 2024).
renal dysfunction (2 papers, 2015 to 2017). "In patients with renal dysfunction, lower body weight or use of concurrent medications that interact with dapsone, we propose that regular monitoring of hemoglobin should be done after initiation of dapsone even if G6PD level is normal." (PMID 25628986, 2015). "The occurrence of hemolysis in patients with normal G6PD level suggest that the hemolysis may be a dose related event as may be seen with elevated dapsone levels in patients with renal dysfunction or due to concurrent use of medications that use the cytochrome P-450 isoenzyme system." (PMID 25628986, 2015).
renal fibrosis (2 papers, 2024 to 2025). A final common manifestation of a wide variety of chronic kidney diseases characterized by glomerulosclerosis and tubulointerstitial fibrosis. "In terms of inhibiting abnormal glycolysis, the natural compound Ovatodiolide inhibits the enzymatic activity and dimer formation of G6PD by specifically targeting its Lys403 site, thereby inhibiting the excessive activation of the pentose phosphate pathway and alleviating renal fibrosis." (PMID 41451126, 2025).
retinal disease (2 papers, 2017 to 2020). "The pathogenesis of G6PD-mediated oxidative biological damage is reviewed and a mechanism for the onset of retinal disease proposed." (PMID 28948126, 2017).
rhabdomyolysis (2 papers, 2024 to 2026). Necrosis or disintegration of skeletal muscle often followed by myoglobinuria. "Additionally, a G6PD-deficient female patient who was treated with tafenoquine had rhabdomyolysis and was discharged after full recovery." (PMID 38365417, 2024).
rheumatic disease (2 papers, 2020 to 2023). "However, only a few studies have been done on the incidence of hemolytic anemia in G6PD-deficient patients taking hydroxychloroquine for rheumatic diseases." (PMID 32884875, 2020).
sarcoidosis (2 papers, 2022 to 2025). Sarcoidosis is a multisystemic disorder of unknown cause characterized by the formation of immune granulomas in involved organs. "However, some UIC STAR cohort key determinant genes, such as ATP6V0D1, FTH1, G6PD, HCK, and SPI1 have been previously associated with sarcoidosis in other studies." (PMID 36311769, 2022).
schizophrenia (2 papers, 2021 to 2024). A major psychotic disorder characterized by abnormalities in the perception or expression of reality. "In the pentose phosphate/glutathione pathways, G6PD was upregulated in schizophrenia but downregulated in ketosis, whereas RPIA was downregulated in both." (PMID 39125835, 2024).
Sjögren’s syndrome (2 papers, 2020 to 2023). "An overwhelming majority of patients (213 of 228) with G6PD testing had SLE (93.9%); RA was found in 30 patients (13.4%), and/or Sjögren’s syndrome in 28 patients (12.2%)." (PMID 32884875, 2020).
skin cutaneous melanoma (2 papers, 2014 to 2022). "In contrast, UVR suppressed the transcription of G6PD, and UA pretreatment further down-regulated G6PD transcription in skin melanoma cells." (PMID 28250388, 2014).
Splenomegaly (2 papers, 2019 to 2020). Abnormal increased size of the spleen. "Oxidative stress (potentially as a result of amoxicillin exposure), which is a known initiator of hemolysis in G6PD deficient patients, may have been severe enough to produce significant, ongoing hemolysis, as well as hepatotoxicity and subsequent splenomegaly in this case presentation." (PMID 31321386, 2019). "CDC recommended that primaquine be provided after arrival in the United States to Congolese refugees with splenomegaly, after confirming normal levels of glucose-6-phosphate dehydrogenase (G6PD)." (PMID 32372751, 2020). "Furthermore, splenomegaly has been associated with ongoing hemolysis in G6PD deficient patients and may explain the lack of reticulocytosis due to splenic sequestration and subsequent destruction." (PMID 31321386, 2019).
acute coronary syndrome (1 paper, 2021). Signs and symptoms related to acute ischemia of the myocardium secondary to coronary artery disease. "Aspirin (ASA) is used as an antiplatelet agent to prevent acute coronary syndromes; however, it has long been believed that this molecule, at high doses, is occasionally capable of triggering a hemolytic crisis in G6PD-deficient subjects." (PMID 34007401, 2021).
age-related hearing loss (1 paper, 2024). "Recent findings supporting the protective role of G6PD overexpression against oxidative stress and age-related hearing loss further lend credence to our speculations." (PMID 38464969, 2024).
angioedema (1 paper, 2025). Swelling involving the deep dermis, subcutaneous, or submucosal tissues, representing localized edema. "An estimated 20–30% of ADEs requiring hospitalization have a prominent genetic component, and the frequency of some ADEs (e.g., ACE inhibitor induced angioedema, G6PD related hemolysis) is well-known to vary by ancestry." (PMID 41282679, 2025).
Astrocytomas (1 paper, 2025). "Astrocytomas, for instance, exhibited elevated levels of glycolysis-related proteins such as hexokinase 2, lactate dehydrogenase A (LDHA), and glucose-6-phosphate dehydrogenase compared to oligodendrogliomas." (PMID 39996200, 2025).
atrophic gastritis (1 paper, 2025). "For example, in atrophic gastritis induced by H. pylori, there is an elevated expression of glucose-6-phosphate 1-dehydrogenase (G6PD) and D-lactate dehydrogenase (D-LDH)." (PMID 40529304, 2025).
bladder tumor (1 paper, 2023). "For instance, 200 μM of zoledronic acid, a medication used to treat various bone diseases, inhibits G6PD activity in bladder tumor cells by interfering with the Ras signaling pathway, which is known to regulate G6PD, leading to decreased G6PD expression." (PMID 38139067, 2023).
bone metastasis (1 paper, 2025). Transfer of a neoplasm from its primary site to bones. "We assessed the association between G6PD activity and the presence of bone metastasis and identified an optimal cutoff value to calculate sensitivity and specificity." (PMID 41514554, 2025). "G6PD activity was significantly higher in patients with bone metastasis and remined an independent predictor in multivariable logistic regression analysis." (PMID 41514554, 2025). "In the multivariable logistic regression analysis, G6PD activity remained the only independent predictor of bone metastasis, with an odds ratio (OR) of 1.08 (95% CI, 1.03–1.12)." (PMID 41514554, 2025). "Also, considering the non-invasive and convenient nature of G6PD activity test, the findings show potential to be combined with other biomarkers to improve predictive power of bone metastasis." (PMID 41514554, 2025). "Furthermore, this study calculated AUC and decided cutoff value of G6PD activity for predicting bone metastasis." (PMID 41514554, 2025). "We compared G6PD activity levels according to presence of bone metastasis." (PMID 41514554, 2025). "Also, ROC analysis was conducted to evaluate the predictive performance of G6PD activity level for bone metastasis." (PMID 41514554, 2025). "Patients were categorized into two groups depending on the presence or absence of bone metastasis, and comparisons were made for age and G6PD activity level." (PMID 41514554, 2025). "We confirmed that G6PD activity was higher in patients with bone metastasis than patients without bone metastasis." (PMID 41514554, 2025). "In addition, due to the cross-sectional design of our study, it is not possible to clearly evaluate changes in G6PD activity before and after the development of bone metastasis." (PMID 41514554, 2025).
breast adenocarcinoma (1 paper, 2019). "The favourable cytotoxicity profile of the most active compounds, 5 and 6, was corroborated by assays performed on human cells (human breast adenocarcinoma (MCF-7) and non-tumour embryonic kidney cells (HEK293T)), even when glucose-6-phosphate dehydrogenase (G6PD) was inhibited." (PMID 31374989, 2019).
Castleman disease (1 paper, 2020). Castleman disease (CD) is a benign lymphoproliferative disorder that may present as a localized or multicentric form. "In this article, we report the first case of a 15-year-old Caucasian male with a history of Marfan and G6PD, who developed SLE, seizures, and Castleman disease." (PMID 33143705, 2020).
cerebral infarct (1 paper, 2021). "Accordingly, it seems reasonable that the enhancement of G6PD activity through HSP27 phosphorylation induced by GGA attenuates protein carbonylation and the severity of cerebral infarct." (PMID 33557752, 2021).
cerebrovascular diseases (1 paper, 2022). "Furthermore, this theory may explain why G6PD-deficient patients show low mortality rates from cardiovascular and cerebrovascular diseases." (PMID 35743352, 2022).
cervical tumors (1 paper, 2022). "The levels of G6PD are increased in some tumors, and the enzyme is regulated by miR-206 and miR-1 in cervical tumors associated with papillomavirus infections, while miR-1 downregulates G6PD in malignant tumors." (PMID 36483029, 2022).
Cirrhosis (1 paper, 2018). A chronic disorder of the liver in which liver tissue becomes scarred and is partially replaced by regenerative nodules and fibrotic tissue resulting in loss of liver function. "For the oxidative phase of PPP enzymes, high G6PD mRNA expression levels were found to be associated with a progression of cirrhosis to HCC and reduced survival rate (P = 0.0209), while PGLS and PGD show no differential expression (P > 0.050)." (PMID 30430110, 2018).
co-infection (1 paper, 2012). "Inhibition of glucose 6-phosphate dehydrogenase (G6PDH) by 6-aminonicotinamide (6-ANAM) decreased cellular NADPH content and induced persistence of Chlamydia with all ultra-structure hallmarks of chlamydial inclusions observed under co-infection conditions." (PMID 23077614, 2012).
colorectal tumor (1 paper, 2023). "We next investigated whether p52-ZER6 regulation of G6PD was limited to colorectal tumor cells or was found in various cancers." (PMID 36977688, 2023).
cyst (1 paper, 2023). A sac-like closed membranous structure that may be empty or contain fluid or amorphous material. "The activities of G6PD, MDH, ME, NH1, and ICD were examined in the cyst samples using isoenzyme method and compared it with the genotyping findings." (PMID 37073115, 2023).
diffuse large B-cell lymphoma (1 paper, 2025). "This case report presents an exacerbation of NL in the rare setting of a history of glucose-6-phosphate dehydrogenase (G6PD) deficiency and a concurrent diagnosis of Epstein-Barr virus (EBV)-positive diffuse large B-cell lymphoma (DLBCL)." (PMID 41523375, 2025).
dystrophinopathies (1 paper, 2021). "Skewed XCI has been demonstrated to play a role in the development of symptomatic phenotypes in female carriers of Duchenne and Becker dystrophinopathies, Wiskott–Aldrich Syndrome, G6PD, and other X-linked disorders." (PMID 34445777, 2021).
enterovirus infection (1 paper, 2023). "Dysregulated redox systems and NF-κB signaling in G6PD-deficient cells have been associated with increased susceptibility to coronavirus and enterovirus infection." (PMID 37753082, 2023).
epithelioid mesothelioma (1 paper, 2023). "For instance, G6PD was clarified participating in cytotoxic T lymphocytes (CTLs) activation and immune escape in epithelioid mesothelioma." (PMID 36909154, 2023).
esophageal tumor (1 paper, 2024). "Single-cell RNA sequencing results also showed that TKT was highly expressed in epithelial tumor tissues of ESCC, whereas G6PD, a rate-limiting enzyme in the oxidative PPP, was only weakly expressed in esophageal tumor tissues." (PMID 39080260, 2024).
Fever (1 paper, 2020). Body temperature elevated above the normal range. "Associations with other RBC variants were less straightforward: α−/αα thalassaemia was associated with higher parasite prevalence in both children and adults; G6PD deficient male hemizygote children, but not females, tolerated higher parasite densities without developing fever." (PMID 31941490, 2020).
fibromyalgia (1 paper, 2023). A chronic disorder of unknown etiology characterized by pain, stiffness, and tenderness in the muscles of neck, shoulders, back, hips, arms, and legs. "Interestingly fibromyalgia rate was significantly higher in the G6PD deficient group (OR 1.98, 95% CI 1.63 to 2.39, P<.001)." (PMID 37753082, 2023).
Fulminant hepatic failure (1 paper, 2020). Hepatic failure refers to the inability of the liver to perform its normal synthetic and metabolic functions, which can result in coagulopathy and alteration in the mental status of a previously healthy individual. "Although being frequent in endemic countries, there is a lack of literature in understanding the synergistic effect of hepatitis E disease and G6PD inadequacy leading to fulminant hepatic failure and increased mortality in the absence of a liver transplant facility." (PMID 33510983, 2020).
Fulminant hepatitis (1 paper, 2024). Acute hepatitis complicated by acute liver failure with hepatic encephalopathy occurring less than 8 weeks after the onset of jaundice. "In the research by Amir Aliabad, there was no discernible difference in the hemoglobin level between children with fulminant hepatitis and those who did not have a G6PD deficit." (PMID 39011425, 2024).
gastric ulcer (1 paper, 2022). An ulcerated lesion in the mucosal surface of the stomach. "Furthermore, G6PD activity in gastric ulcers and erythrocytes in lead‐exposed populations could be rescued by NAC treatment, indicating a correlation between G6PD and NAC." (PMID 35666067, 2022).
glomerulonephritis (1 paper, 2015). A renal disorder characterized by damage in the glomeruli. "We report a case of dapsone induced hemolytic anemia in a patient with ANCA associated glomerulonephritis and normal G6PD level." (PMID 25628986, 2015).
glomerulosclerosis (1 paper, 2022). A hardening of the kidney glomerulus caused by scarring of the blood vessels. "In an animal model after CS exposure for 4 months, CS caused tubular injury and glomerulosclerosis and induced fibrosis, autophagy, and G6PD." (PMID 35387262, 2022).
glucose metabolism disorder (1 paper, 2024). "Among these, the most representative mechanisms are glucose metabolism disorder and oxidative stress, with glucose-6-phosphate dehydrogenase (G6PD) being a key factor in both." (PMID 39621725, 2024).
Granuloma (1 paper, 2023). A compact, organized collection of mature mononuclear phagocytes, which may be but is not necessarily accompanied by accessory features such as necrosis. "We added 6-aminonicotinamide (6AN), a G6PD inhibitor, and 2,5-dichloro-N-(5-chloro-2-benzoxazolyl)-benzenesulfonamide, an FBP1 inhibitor (FBPi) in this in vitro granuloma model." (PMID 38038136, 2023).
hemorrhagic disease (1 paper, 2020). Spontaneous or near spontaneous bleeding caused by a defect in clotting mechanisms (blood coagulation disorders) or another abnormality causing a structural flaw in the blood vessels (hemostatic disorders). "The contraindications of ozone therapy include: allergy to ozone, hyperthyroidism, deficiency of Glucose-6-phosphate Dehydrogenase (G6-PD), spinal canal stenosis, lateral recess stenosis, vertebral slippage, hemorrhagic disease, and severe hepatorenal insufficiency." (PMID 32312002, 2020).
hyperhomocysteinemia (1 paper, 2011). A serious metabolic condition caused by mutations in the MTHFR gene, medications, or nutritional deficiency. "It has been reported that hyperhomocysteinemia led to significant lowering of G6PD activity." (PMID 22194889, 2011).
ischemia (1 paper, 2021). A hypoperfusion of the BLOOD through an organ or tissue caused by a PATHOLOGIC CONSTRICTION or obstruction of its BLOOD VESSELS, or an absence of BLOOD CIRCULATION. "The current study demonstrated that GGA can protect the rat cerebral cortex against ischemia–reperfusion injury by increasing the endogenous phosphorylation of HSP27, which activates G6PD activity, during ischemia–reperfusion." (PMID 33557752, 2021).
kidney damage (1 paper, 2024). "Taken together, our study demonstrates that the urine G6PD activity is decreased in patients with DKD and is independently associated with relatively early kidney damage." (PMID 39140974, 2024).
leiomyoma (1 paper, 2011). A well-circumscribed benign smooth muscle neoplasm characterized by the presence of spindle cells with cigar-shaped nuclei, interlacing fascicles, and a whorled pattern. "The random inactivation of the X chromosome-bearing genes for isoenzyme types A and B of glucose-6-phosphate dehydrogenase was used to establish the clonal origin of neoplasms in informative women with leiomyomas." (PMID 23908816, 2011). "Whereas the samples of normal uterine tissue exhibited both G6PD isoenzymes A and B (distinguished by the appearance of two bands migrating through a starch gel electrophoresis), the samples from leiomyomas had either G6PD isoenzyme type A or B, but not both." (PMID 23908816, 2011).
Macrothrombocytopenia (1 paper, 2025). "Although G6PD levels were very low, the history of transfusions and macrothrombocytopenia prompted preliminary testing for a GATA1 mutation, which was negative." (PMID 40941697, 2025).
macular edema (1 paper, 2024). "The results showed that G6PD, triglyceride, cholesterol, IL-8, TNF-α, and macular edema were influencing factors of DR in T2DM patients." (PMID 39621725, 2024). "Logistic regression analysis showed G6PD, triglyceride, cholesterol, IL-8, TNF-α, and macular edema were influencing factors for T2DM with DR." (PMID 39621725, 2024).
metastatic cancer (1 paper, 2020). A carcinoma which has spread from the original site of growth to another anatomic site. "In this study, we provide experimental evidence that combinatory metabolic inhibition against FAO and G6PD inhibition with clinically available drugs successfully suppresses metastatic cancer progression." (PMID 32487689, 2020).
metastatic melanoma (1 paper, 2020). A melanoma that has spread from its primary site to another anatomic site. "TNBC and metastatic melanoma cell lines show overexpression of let-7a which represses cell proliferation, increases ROS, and downregulates proteins involved in glucose metabolism including glucose 6-phosphate dehydrogenase (G6PD)." (PMID 35006436, 2020).